ABR-AS1 (ABR antisense RNA 1)
Gene: Long non-coding RNA gene on chromosome 17 (1,181,627 to 1,191,183, forward strand). Ensembl gene ENSG00000235361.
Gene Ontology:
Biological process: SRP-dependent cotranslational protein targeting to membrane, signal sequence recognition
Cellular component: signal recognition particle, endoplasmic reticulum targeting